CPS1 (carbamoyl-phosphate synthase 1)
Diseases named in the same sentence as CPS1 in open-access papers (continued):
Sharing a sentence is not in itself a finding about the gene and the disease.
lung cancer (17 papers, 2018 to 2026). A malignant neoplasm involving the lung. "In this study, we investigated the role of CPS1 in promoting lung cancer metastasis and its underlying mechanism." (PMID 41356199, 2026). "The failure of 15N incorporation into pyrimidine precursors in the sgCps1 liver is consistent with the protumorigenic role of CPS1 in lung cancer by maintaining the pyrimidine pool, yet it contradicts the protumorigenic function of CPS1-deficiency in HCC." (PMID 41512056, 2026). "The observed suppression of ATM expression in CPS1-overexpressing lung carcinoma cells creates a compounded DNA repair deficiency phenotype, mechanistically explaining the enhanced radiation sensitivity." (PMID 40565327, 2025). "CPS1 emerges as a dual-functional candidate in lung cancer patients, serving both as a potential diagnostic and prognostic biomarker and a radiosensitizing therapeutic target to optimize radiotherapy efficacy through its novel role in metabolic regulation of DNA damage response pathways." (PMID 40565327, 2025). "The inhibition of CPS1 in lung cancer cells carrying KRAS/LKB1 mutations suppressed tumor growth." (PMID 35251577, 2022). "To further validate CPS1's role in promoting tumor metastasis, we tested an alternative metastatic mouse model involving tail vein injection of metastatic lung cancer cells into immunocompetent C57BL/6 mouse." (PMID 41356199, 2026). "Our findings demonstrate that reducing CPS1 expression, either through genetic manipulation or enzymatic inhibition, significantly reduces lung cancer metastasis in mice, establishing a robust foundation for future translational research." (PMID 41356199, 2026). "This suggests that CPS1-mediated urea cycle reprogramming likely serves as the primary driver of fumarate accumulation during lung cancer metastasis." (PMID 41356199, 2026). "Collectively, our work establishes CPS1 as a critical metabolic driver of metastasis and a viable therapeutic target for lung cancer metastasis." (PMID 41356199, 2026). "Overexpression of the rate-limiting enzyme CPS1 is sufficient to drive lung cancer cell migration/spreading and metastasis to distal organs." (PMID 41356199, 2026). "While transwell assay showed that overexpression of CPS1 in primary lung cancer cells (L0) led to increased cell migration, vitamin C (VC), known to activate DNA demethylases like TET2 29, dramatically rescued this effect." (PMID 41356199, 2026). "In summary, this study identified the urea cycle enzyme CPS1 as a pivotal promoter of lung cancer metastasis through a defined metabolic-epigenetic pathway." (PMID 41356199, 2026). "In this study, CPS1 is highly expressed in metastatic lung cancer cells and elevated CPS1 activity accumulates urea cycle-derived fumarate to inhibit TET2 activity, which regulates miR200a-EMT axis in tumor metastasis and reduces PD-L1 in tumor immunity." (PMID 41356199, 2026). "Critically, either reducing CPS1 expression or inhibiting its activity in metastatic cells significantly reduced metastasis of lung cancer cells in mice." (PMID 41356199, 2026). "To understand the mechanism of CPS1-mediated lung cancer cell migration, we used RNA-sequencing to compare the transcriptome between L6 cells expressing shRNA targeting CPS1 (shCPS1) and control (shScr)." (PMID 41356199, 2026). "High CPS1 expression significantly correlated with poor patient overall survival and disease-free survival in lung cancer patient, with average hazard ratios of 5.84 and 2.74, respectively." (PMID 41356199, 2026). "Nevertheless, identifying overexpressed CPS1 and activated urea cycle in lung cancer patients, ideally at localized stage, offers a promising opportunity for personalized treatment strategies to improve patient outcomes." (PMID 41356199, 2026). "Immunohistochemistry studies showed a clear increase in CPS1 expression in metastatic lesions from lung cancer patients." (PMID 41356199, 2026).
lung cancer (continued). "Knocking down CPS1 effectively reduced DNA methylation of miR200a in these metastatic cells, suggesting that CPS1 induced DNA methylation of miR200a to promote the migration of lung cancer cells." (PMID 41356199, 2026). "This suggests that elevated CPS1 activity drives lung cancer metastasis by accumulating fumarate to mediate the TET2 activity, miR200a DNA methylation and the EMT program." (PMID 41356199, 2026). "This study demonstrated that the urea cycle enzyme CPS1 functions as a DDR pathway modulator in lung cancer radiobiology." (PMID 40565327, 2025). "The proliferation assay demonstrated significantly impaired cellular proliferation in CPS1-overexpressing lung cancer cells compared to vector controls following 8 Gy ionizing radiation." (PMID 40565327, 2025). "Integrated analysis of CPS1 co-expression networks in TCGA lung cancer cohorts via cBioPortal identified 173 significantly correlated genes." (PMID 40565327, 2025). "Mechanistic investigations further revealed CPS1 as a putative modulator of the DDR pathway in lung carcinoma, orchestrating radiation-induced genomic instability through coordinated regulation of DDR effectors." (PMID 40565327, 2025). "Silencing CPS1 in KRAS/LKB1-mutant lung cancer cells has been found to lead to pyrimidine depletion, S-phase progression, DNA-polymerase stalling, DNA damage, and cell death." (PMID 36983664, 2023). "To further establish the clinical relevance of the synthetic lethality of DEX in LKB1-mutant lung cancer, we chose a NSCLC PDX adenocarcinoma (LTL-657) from a bank of NSCLC PDXs based on high expression of CPS1 and somatic mutations of KRAS and LKB1." (PMID 37035141, 2023). "CPS1 has been reported to promote maintain pyrimidine pools and DNA synthesis and thus facilitate tumor growth in lung cancer." (PMID 35655758, 2022). "While AMPK reportedly inhibits CPS1 expression in KRAS-mutant lung cancer cells, our results show that it also inhibits CPS1 expression in HCC cells without KRAS mutation." (PMID 33917483, 2021). "It was demonstrated that STK11/LKB1 downregulates CPS1 transcription via AMPK-mediated effects and that KRAS/STK11 mutant lung cancer cells upregulate expression of CPS1, allowing cell division and tumor development." (PMID 34831355, 2021). "Surprisingly, CPS1 expression was found predominantly in the cytoplasm in these lung cancer cells, in contrast to the CPS1 only expressed inside the mitochondria in the liver and intestinal epithelial cells." (PMID 29895729, 2018). "Indeed, our study detected negligible CPS1 expression in normal lung cells and low levels in para-tumor tissues or primary lung cancer cells." (PMID 41356199, 2026). "Combining CPS1 inhibition and PD-1 blockade effectively suppressed lung cancer metastasis and significantly prolonged the survival of mice, by directly targeting tumor cells via the metabolic pathway while concurrently reinvigorating the anti-tumor activity of CD8+ T cells." (PMID 41356199, 2026). "Furthermore, Western blot analysis of lung cancer patient samples revealed a significant increase in CPS1 within metastatic tumor tissues." (PMID 41356199, 2026). "Furthermore, analysis of TCGA lung cancer data revealed a correlation between high mRNA levels of CPS1 and reduced overall survival, albeit with less dramatic hazard ratios (1.49 for LUAD and 1.34 for LUAD + LUSC)." (PMID 41356199, 2026).
lung cancer (continued). "While this inhibitory effect in organoids likely targeted tumor growth rather than metastasis directly, consistent with previous studies 12, it suggests the translational potential of CPS1 inhibitors for lung cancer patients presenting with early signs of metastasis." (PMID 41356199, 2026). "To investigate the role of CPS1 in lung cancer progression and metastasis, we generated GEM models harboring the following alleles: (a) KP mice with wild-type Cps1 alleles; and (b) KPC mice, which are KP mice with homozygously floxed Cps1 alleles." (PMID 41356199, 2026). "Notably, our findings align with CPS1’s radiation-sensitizing role in lung cancer, where co-expression network analysis and post-irradiation Western blot assays revealed enzyme activity-dependent modulation of DNA damage repair and oxidative stress pathways." (PMID 40565327, 2025). "Our study identified CPS1 as a critical radiosensitizing factor in lung cancer." (PMID 40565327, 2025). "In lung cancer cells, loss of LKB1 and activation of K-RAS led to increased expression of mitochondrial carbamoyl phosphate synthetase-1 (CPS1), increasing the abundance of carbamoyl phosphate intermediates that can exit the mitochondria to be utilized by the de novo pyrimidine synthesis pathways." (PMID 31108873, 2019). "Taken together, these findings not only pinpoint a novel metabolic reprogramming process driving lung cancer metastasis but also provided compelling evidence that targeting urea cycle, especially through CPS1 inhibition, could be an effective therapeutic strategy." (PMID 41356199, 2026). "However, a recent report in lung cancer suggests that CPS1 may be crucial for pyrimidine maintenance and DNA synthesis in KRAS mutant cells." (PMID 40000871, 2025). "To investigate how CPS1 influences TET2-mediated demethylation in metastatic cells, we performed metabolomic analysis on primary (L0) and metastatic (L2 and L6) lung cancer cells." (PMID 41356199, 2026). "Although NAGS is expressed in lung cancer derived cell lines, expression of the NAGS gene and its product was not evaluated in tumors with aberrant expression of CPS1 and citrin." (PMID 37047726, 2023).
urea cycle disorder (16 papers, 2016 to 2025). A genetic inborn error of metabolism characterized by the deficiency of one of the enzymes necessary for the urea cycle. "The deficiency of bicarbonate for the CPS1 reaction contributes to the proximal urea cycle disorder phenotype." (PMID 40710547, 2025). "Six of the 61 patients with small molecule disorders had a urea cycle disorder (CPS1, OTC, and ASL deficiencies)." (PMID 36101823, 2022). "On the other side, CPS1 deficiency is a rare autosomal genetics-based disease belonging to urea cycle disorders (UCD), producing a reduced metabolism of proteins and nitrogen and elevated ammonia levels in the cell." (PMID 32498414, 2020). "Additionally, in two 3-MGA patients [P13, P40] we found molecular variants in the CPS1, a non MD-related gene linked to urea cycle disorder." (PMID 27290639, 2016). "Deficiency of CPS1 (CPS1D) is classified as a rare autosomal recessive disorder, with clinical manifestations that closely resemble those of other proximal urea cycle disorders." (PMID 40710547, 2025). "We reported the variants of CPS1, ASS, ASL and OTC detected in the patients with urea cycle disorders through a nation-wide survey in Japan." (PMID 36303552, 2022). "Four genes (OTC, ASL, CPS1, and ASS1) were responsible for urea cycle disorders, accounting for 14.6% (13/89)." (PMID 34733806, 2021). "NAGSD is the only urea cycle disorder that can be treated with a single drug, N-carbamylglutamate (NCG), which can activate CPS1 and completely restore ureagenesis in patients with NAGSD." (PMID 30337552, 2018). "CPS1, carbamoyl phosphate synthetase 1; NAGS, N-acetylglutamate synthase; ORNT1, ornithine translocase; OTC, ornithine transcarbamylase; UCD, urea cycle disorders." (PMID 37480106, 2023).
lung adenocarcinoma (15 papers, 2018 to 2026). A carcinoma that arises from the lung and is characterized by the presence of malignant glandular epithelial cells. "Our analysis replicated the association between CPS1 overexpression and unfavorable outcomes in patients with lung adenocarcinoma." (PMID 37047726, 2023). "It has been reported that CPS1 promotes pyrimidine synthesis in the aggressive subset of lung adenocarcinoma with mutant KRAS plus LKB1 loss and supports tumor growth." (PMID 33493519, 2021). "Therefore, we queried cBioPortal for the association between NAGS, CPS1, and citrin mRNA expression levels and outcomes of patients with glioblastoma, glioblastoma multiforme, lung adenocarcinoma, and stomach adenocarcinoma." (PMID 37047726, 2023). "There was a trend towards a worse outcome (p = 0.07) in patients exhibiting the lowest quartile of NAGS mRNA expression in lung adenocarcinoma, while the outcome was worse for patients with the highest CPS1 mRNA expression in lung adenocarcinoma." (PMID 37047726, 2023). "CPS1 and citrin protein abundance data were available for individual glioblastoma and lung adenocarcinoma samples." (PMID 37047726, 2023). "The correlation between CPS1 and citrin protein abundance was weak in individual glioblastoma and lung adenocarcinoma samples." (PMID 37047726, 2023). "NAGS and CPS1 had a similar median mRNA expression in lung adenocarcinoma (LUAD, n = 517) and matched normal tissue, while citrin was overexpressed in LUAD." (PMID 37047726, 2023). "Histone modifications, CTCF, and RNA polymerase II binding to NAGS, CPS1, and citrin regulatory regions in the liver, lung, and A549 lung adenocarcinoma cells suggest that all three genes appear to be poised for expression in the lung tissue." (PMID 37047726, 2023). "This suggests markedly lower NAGS and CPS1 expression in glioblastoma multiforme, glioma, lung adenocarcinoma, stomach adenocarcinoma, and stomach and esophageal carcinoma than in the liver and small intestine." (PMID 37047726, 2023). "CPS1 was upregulated in many types of tumors, including lung adenocarcinoma, glioblastoma multiforme, and gastric cancer, and indicated a poor prognosis." (PMID 36090899, 2022). "Clustering analysis of lung adenocarcinoma gene expression data demonstrated that NTS expression is highly positively correlated with the expression of the oncogenic factor CPS1." (PMID 33493519, 2021). "Remarkably, it was shown that transcription of CPS1 is negatively regulated by liver kinase B1 (also known as serine/threonine kinase 11) in lung adenocarcinoma cell lines." (PMID 31248089, 2019). "CPS-1 is related to cell growth and metabolite levels associated with nucleic acid biosynthesis pathway, as shown by CPS-1 knockdown in lung adenocarcinoma." (PMID 29456966, 2018). "Patterns of DNase hypersensitive sites and histone modifications in the upstream regulatory regions of NAGS, CPS1, and citrin genes were similar in liver tissue, lung tissue, and A549 lung adenocarcinoma cells despite different expression levels of the three genes in the liver and lung." (PMID 37047726, 2023). "However, the fraction of glioblastoma, glioblastoma multiforme, lung adenocarcinoma, and stomach adenocarcinoma samples with sequence variants in NAGS, CPS1, and citrin was low." (PMID 37047726, 2023). "We queried the cBioPortal database to determine whether the expression of NAGS, CPS1, and citrin in glioblastoma multiforme, glioma, stomach adenocarcinoma, and lung adenocarcinoma correlated with the patient outcomes for these four tumor types." (PMID 37047726, 2023). "This is consistent with aberrant CPS1 expression in lung adenocarcinoma." (PMID 37047726, 2023). "First, we compared the difference in mRNA expression between normal and tumor groups in lung adenocarcinoma with CPS1 and SMS genes in the TCGA and GEPIA2 databases, and also validated them in the GEO database, and analyzed the protein expression level of data from CPTAC in the UALCAN database." (PMID 37709932, 2023).
lung adenocarcinoma (continued). "In lung adenocarcinoma cells, inhibition of CPS1 expression was found to reduce tumor growth." (PMID 30967136, 2019). "Therefore, we evaluated the NAGS, CPS1, and citrin mRNA and protein expression in glioblastoma multiforme, glioma, lung adenocarcinoma, stomach adenocarcinoma, and stomach and esophageal carcinoma in comparison to the expression of the three genes in the liver and small intestine." (PMID 37047726, 2023). "Studies have shown a link between LKB1-negative lung adenocarcinoma (LADC) patients and CPS1 expression 12, suggesting a potential role for CPS1 in this specific cancer subtype." (PMID 41356199, 2026). "First, we identified two central genes, CPS1 and SMS, that affect the prognosis of lung adenocarcinoma by stepwise multivariate Cox analysis and constructed a prognostic model associated with Arg and Pro metabolism." (PMID 37709932, 2023). "Among other regulators, CPS1 is activated in the presence of N-acetyl-L-glutamate (NAG) and its transcription is negatively regulated by liver kinase B1 in lung adenocarcinoma cell lines." (PMID 35008510, 2021). "Employing 117 machine learning algorithm combinations, we develop a robust five-gene prognostic signature (FAM83A, RHOV, CPS1, STRIP2, SLC2A1) for lung adenocarcinoma (LUAD) with area under the curve values of 0.692, 0.688, and 0.614 for 1-, 3-, and 5-year overall survival, respectively." (PMID 42062606, 2026). "More than 90% of the lung adenocarcinoma samples were diploid for NAGS, CPS1, and citrin genes." (PMID 37047726, 2023). "The expression of NTS was highly correlated with that of CPS1, fibrinogen gamma (FGG), and glutathione peroxidase 2 (GPX2) in a subgroup of lung adenocarcinoma samples, suggesting these genes might belong to a gene coexpression network." (PMID 33493519, 2021). "Therefore, we examined whether individual glioblastoma, glioblastoma multiforme, lung adenocarcinoma, and stomach adenocarcinoma samples exhibit the overexpression of NAGS, CPS1, and citrin mRNA." (PMID 37047726, 2023). "However, the association between lower NAGS expression and unfavorable outcomes in patients with lung adenocarcinoma is consistent with the absence of correlated NAGS and CPS1 expression in this tumor type." (PMID 37047726, 2023).